CCL28 (C-C motif chemokine ligand 28)
Diseases named in the same sentence as CCL28 in open-access papers (continued):
Sharing a sentence is not in itself a finding about the gene and the disease.
tumor (continued). "In the case of this situation, this could mean that CCL28 can attract immune cells to the tumor microenvironment, thereby promoting immune surveillance and response to the tumor." (PMID 39267764, 2024). "Further, we evaluated the expression levels of CCL28 within the tumor tissue." (PMID 39075504, 2024). "Moreover, the production of cytokines such as IL-2, IL-4, IL-6, IL-7, IFN-γ, IFN-α, TNF-α, CCL7, and CCL28 can stimulate an anti-tumor response." (PMID 38533507, 2024). "While CCL28 has both anti- and pro-tumor properties, the latter dominate in the hypoxic cancerous Tumor Micro-Environment (TME) and involves stimulating the chemotaxis of myofibroblasts and various lymphocyte types, including Tregs, to the tumor site via CCR10 activation." (PMID 36841432, 2023). "Functionally, we observed that FOSL2 overexpression increased tumour growth and Treg cell infiltration, which could be reversed by blockade of CCL28 activity in vivo, indicating its potential as a therapeutic target." (PMID 37380804, 2023). "Tumor hypoxia can activate CCL28 expression to recruit Treg, and induce tumor tolerance." (PMID 36676763, 2023). "Interestingly, anti-CCL28 treatment significantly reduced tumour size compared to the isotype control." (PMID 37380804, 2023). "The mucosal chemokine CCL28 is a promising target for immunotherapy drug development due to its elevated expression level in epithelial cells and critical role in creating and maintaining an immunosuppressive tumor microenvironment." (PMID 36841432, 2023). "Forced expression of CCL28 in mouse ovarian cancer cells causes robust Treg cells accumulation, but also results in increased VEGF levels and significantly increases blood vessel development, which is associated with rapid tumor angiogenesis." (PMID 35759090, 2022). "In addition, tumor hypoxia induces the expression of CCL28, CXCL12 and CXCR4, selectively enhanced the recruitment of T(reg) cells, thereby inducing tumor tolerance and new angiogenesis." (PMID 36226050, 2022). "In addition, tumor cells regulate chemokine receptor 28 (CCL28), thus recruiting Treg cells, enhancing the immune tolerance, and promoting the angiogenesis." (PMID 34604045, 2021). "In addition, at the protein level, FGF18, IL23A, LIF, and VGF stained more deeply in tumor tissues than in normal tissues, while CCL28 and SLIT2 were only deeply stained in normal intestinal mucosal tissues according to the Human Protein Atlas." (PMID 34017356, 2021). "Furthermore, CCL28, mucosa-associated epithelial chemokine (MEC), has been suggested to have something to do with tumor progression and the involvement in inflammation." (PMID 33802957, 2021). "Indeed, a previous study on ovarian cancer suggested that hypoxia increases the secretion of CCL28 to enhance the recruitment of Tregs, which in turn promotes angiogenesis and tumor tolerance." (PMID 33422072, 2021). "CCL28 and CCL27 participate in the anticancer response of the immune system, causing an infiltration of the tumor by anticancer NK cells, which leads to improved prognosis with an increased expression of these chemokines in the tumor." (PMID 33076281, 2020). "Here we describe that CCL28/CCR10 axis could be active outside the tumor core and that it could represent a connection between the margin of the tumor and the peripheral healthy tissue." (PMID 33066172, 2020). "Further, the hypoxic conditions that result from VEGF-mediated abnormalities in the tumor vasculature can also induce secretion of chemokine CCL28 from tumor cells that leads to Treg recruitment, and accumulation of immunosuppressive M2 tumor-associated macrophages." (PMID 33250900, 2020). "In practice, others have found that tumor hypoxia upregulates CCL28, a chemokine that recruits CD4+CD25+FOXP3+ Treg cells in an ovarian cancer mouse model, linking it to a more tolerigenic TME and increased tumor vascularization via vascular endothelial growth factor A." (PMID 35310881, 2020).
tumor (continued). "Tumor associated macrophages (TAMs) and myeloid suppressor cells (MDSCs) release chemokines, such as CCL17, CCL22, CCL5, CCL6 or CCL28, depending on the tumor type, to attract Tregs expressing the chemokine receptors CCR4, CCR5, CCR10 and CXCR3 from secondary lymphoid tissues to the tumor." (PMID 32937953, 2020). "Moreover, hypoxia induces the recruitment of Tregs to the tumor microenvironment through CCL28 expression on tumor cells and the expression of Foxp3, thereby promoting intratumoral immune suppression." (PMID 31083487, 2019). "Specifically, hypoxia may stimulate the expression of chemokine CCL28, which in turn plays a major role in recruiting regulatory T cells to the tumor site and accelerating tumor growth." (PMID 27716621, 2016). "Significantly, we observed an acceleration in tumor growth when a cell clone that overexpressed CCL28 was injected and allowed to grow in mice, and such growing advantages were mainly due to CCL28 overexpression and independent of immunoprotective differences among individuals." (PMID 27716621, 2016). "However, evidences supporting a direct role of CCL28 on tumor angiogenesis were presented in the present study." (PMID 27250766, 2016). "And CCL28 overexpression tumor exhibited higher Ki67 positive rate." (PMID 27716621, 2016). "CCL28 was highly expressed in 46.7% (7/15) of the tumor samples." (PMID 27250766, 2016). "In addition, the tumor microvascular density was much higher in CCL28 high expression tumors (p < 0.05)." (PMID 27250766, 2016). "However, little is known about the mechanism of CCL28 in tumor vascular normalization." (PMID 39075504, 2024). "A prognostic index for tumor samples could be calculated by the formula: IRGPI = (HTN3 expression * 0.096) + (CTSG expression * −0.152) + (MAPT expression * 0.122) + (CCL28 expression * −0.094) + (PTX3 expression * 0.138) + (SEMA3G expression * −0.140) + (USP2 expression * 0.107)." (PMID 36845378, 2023). "Furthermore, CCL28 secreted by hypoxic tumor cells attract Treg cells in to the tumor niche." (PMID 37056346, 2023). "CCL28 expression was reportedly induced by tumor cells under hypoxia, and could recruit Tregs24." (PMID 36859428, 2023). "Furthermore, overexpression of CCL28 promoted tumor growth and Treg infiltration in vivo." (PMID 27716621, 2016). "Therefore, the current data suggest that CCL28 upregulation promotes HCC tumor growth in vivo." (PMID 27716621, 2016). "This review compiles current knowledge on the significance of lesser-known chemokines in MM tumor processes, including CXCL13, CCR2 ligands (CCL2 [MCP-1], CCL7 [MCP-3]), CCL4, CCL5 (RANTES), CCL17, CCL20, CCL27, CCL28, and CX3CL1 (fractalkine)." (PMID 41749925, 2026). "In previous studies, CCL-28, FGF-19 and IL-2 were mostly investigated in immune disorders and tumor treatment 51-54, and neurturin was mainly discussed in muscular, neurodegenerative and psychiatric disorders 55,56." (PMID 40225870, 2025). "Lymphatic endothelial cells (LECs) expressing CCR10, regulated by VEGF-D and TNF-α migrate towards tumor-derived CCL27 and CCL28; VEGF-D is essential for in vivo lymphatic vessel formation and metastasis." (PMID 41050670, 2025). "Both DCA and LCA can also trigger tumor cell TGR5 activation, leading to CCL28-mediated recruitment of regulatory T cells (Tregs)." (PMID 40821794, 2025). "Abnormal tumor vessels further exacerbate hypoxia, which in turn increases the secretion of chemotactic cytokines - including CCL2, CCL22, CCL28, CXCL8, and CXCL12 - that recruit immunosuppressive MDSCs, M2-like TAMs, and Tregs into the tumor." (PMID 41019982, 2025). "Tumor cells and stromal cells recruit Tregs to the tumor site primarily by secreting chemokines such as CCL22, CCL17 (binding to CCR4 on Tregs), and CCL28 (binding to CCR10)." (PMID 40698080, 2025). "The presence of hypoxia in ovarian cancer triggers the overexpression of CCL28, a ligand specific to CCR10, by tumor cells." (PMID 39000453, 2024).
tumor (continued). "This hypoxic microenvironment triggers alternative pro-angiogenesis molecular pathways in tumor or stromal cells within the tumor microenvironment, including FGF-2, HGF, DLL4/Notch, CCL28, and others." (PMID 39075504, 2024). "Expression of CCL28, APP, EHF and LINC00342, among others, is increased in LP cells relative to the basal tumor." (PMID 39478117, 2024). "CEBPB and Sp1 can potentially regulate CCL28, while only CEBPB was highly expressed in hypoxic tumor cells." (PMID 39075504, 2024). "This heightened expression of CCL28 in hypoxic conditions fosters the attraction of CCR10-expressing Treg cells to the tumor site, thereby facilitating tumor tolerance and angiogenesis." (PMID 39000453, 2024). "On the other hand, the CCL28, CXCL14 and CX3CL1 expression levels were higher than those in other tumours." (PMID 37484803, 2023). "Treg cells are mainly recruited to the tumor microenvironment by chemokines such as CCL1, CCL17, CCL22, CCL28, CXCL9, CXCL10, and CXCL11." (PMID 37686093, 2023). "In one study, overexpression of CCL28 (inflammatory chemokine) and underexpression of DKK3 (a tumour suppressor and prognostic marker) were predictive of pCR." (PMID 35205743, 2022). "The expression of HMGB1 and TLR4 was significantly high in tumor tissue compared with that in normal tissue, the expression of CCL28, KLF2 and TNFSF18 in tumor were similar to normal tissues." (PMID 36204682, 2022). "By binding to its receptor, CCR10, CCL28 can effectively recruit CCR10+ Treg cells to the tumor site, thus suppressing the functions of effector T-cells and promoting the tumor growth." (PMID 33422072, 2021). "Hypoxic cancer cells can upregulate C-C motif chemokine ligand 28 (CCL28) levels via HIF-1α, stimulating the recruitment of Tregs into the tumor microenvironment and allowing cancer cells to avoid immune surveillance." (PMID 34298879, 2021). "Tregs are selectively trended into tumor tissues by tumor cells in a CCL22- and CCL28-dependent manner; subsequent Treg-induced secretion of VEGF-A by cancer cells promotes endothelial cell proliferation." (PMID 34063848, 2021). "In fact, CXCR4, SPP1, ACKR3, CCL2, PTGS2, CD274 (PD-L1), CXCL11 were upregulated while CCL28, CCR1, CCR7 were down regulated in both comparisons (blue boxes), suggesting this as a signature specific of the core region of the tumor." (PMID 33066172, 2020). "A hypoxic state of the tumor also induces the upregulation of C-C motif chemokine 11 (CCL11) and chemokine (C-C motif) ligand 28 (CCL28) capable to recruit Tregs into the tumor microenvironment." (PMID 31370258, 2019). "Chemokines in the omental tumor tissues revealed some changes as follows: 1) the decreased levels in CCL26, CCL28, CXCL1-3, CXCL8 and CXCL16; 2) the increased level in CCL24; and 3) the conserved level in CCL20 compared to the parental cells." (PMID 27723802, 2016). "Because immunotherapy using NK cells suffers from the inability of these cells to migrate into tumor stroma, it is now feasible to direct these cells toward sites of tumor growth, particularly those secreting CCL27 and CCL28." (PMID 27807435, 2016). "The role of HIF-1a has also been identified in promoting the recruitment of Treg cells to the tumor microenvironment via over-expression of cytokines and chemokines, such as TGF-β CCL28 by hypoxic tumor cells." (PMID 27066006, 2016). "It has been shown that increased expression of CCL28 during angiogenesis allows recruitment of the CCR10+ T-regulatory cells, which protect tumor cells from immune clearance and increase tumor angiogenesis and vascularization." (PMID 24384839, 2013). "In a mouse BC model, Tregs also controlled the activation of natural killer (NK) cells in lymph nodes to promote BC lymph node metastasis, as an increased function of CCL28 in the hypoxic environment within the TME can promote Treg recruitment and increase the level of tumor-derived VEGF secretion." (PMID 39329710, 2024).
tumor (continued). "Notably, CCL28 and CCL27 direct the migration of plasma cells to mucosal sites during breast cancer anti-tumor response, correlating with improved prognosis." (PMID 38533507, 2024). "In tumor tissues under hypoxic environments, CCR3 expressed in vascular endothelial cells, and CCR10 expressed in Treg cells, both receptors for CCL28, have been reported to contribute to promoting the angiogenesis process through hypoxia-induced CCL28." (PMID 38534417, 2024). "We found that NUP107 was positively correlated with chemokines such as CCL28 and CXCL8 (r = 0.310, p < 0.001), and the chemokine receptors CCR8 and CXCR4 suggesting that NUP107 overexpression may recruit immune cells to the tumor tissues." (PMID 36952458, 2023). "Upon expansion of abnormal tumor blood vessels, hypoxic microenvironment in tumors leads to the upregulation of chemokine (C-C motif) ligand-22 (CCL-22) and chemokine (C-C motif) ligand-28 (CCL-28), which are both involved in the recruitment of Tregs into tumors." (PMID 36439137, 2022). "Furthermore, hypoxia increased the expression of CCL28 and TGF-β and engaged in the process of recruiting Treg cells, thereby regulating the inhibitory action of Teff cells to promote angiogenesis and tumor tolerance." (PMID 36118856, 2022). "In addition, it has been reported that hypoxia induces the expression of CCL28, a CCR10 ligand, by tumor cells of ovarian and liver cancers, which recruits CCR10-expressing Treg cells into tumor tissues." (PMID 34885241, 2021). "In our samples, the mRNAs of CCL22 and CCL28, two chemokines to which Tregs can respond, did not increase and CCL28 even decreased in tumor." (PMID 28290464, 2017). "Several chemokine-chemokine receptor pairs have been proposed to be responsible for recruiting Tregs to tumors including chemokine receptors CCR4, CCR10, CCR8 or CXCR3 expressed on infiltrating Tregs, responding to CCL22, CCL28, CCL1 or CXCL9-11 in the tumor microenvironment, respectively." (PMID 28290464, 2017). "Hypoxia-induced CCL28 secretion by the tumor has been shown to induce the CCR-10-dependent recruitment of Treg to tumors, exacerbating the immunosuppressive pressure that allows the tumor to evade host destruction." (PMID 27066484, 2016). "Previous studies have proven that CCL28 could recruit CCR3+ regulatory T cells (Tregs) homing to the tumor, which thereafter could promote tumor immunosuppression and tumor angiogenesis by secreting VEGF13." (PMID 27250766, 2016). "Consequently, NK cells can be targeted toward the growth of tumor cells that secrete CCL27 and CCL28." (PMID 27807435, 2016). "Given the correlation of high level CCL28 and hypoxia, we further hypothesized that CCL28 might promote in vivo growth of HCC cells due to the highly hypoxic microenvironment in tumor." (PMID 27716621, 2016). "However, other CCLs, including CCL2, CCL3, CCL11, CCL26, and CCL28, did not exhibit significant changes in expression during tumor progression." (PMID 39859340, 2025). "However, the suppression effect is more pronounced after knocking out CCL28 than the control group (LLC-NC), and CCL28 knockout with supplementing RA could further synergistically inhibit tumor growth." (PMID 39075504, 2024). "In hypoxia, for instance, hypoxia enhances the secretion of CCL28 by tumor cells in a HIF-1α-dependent mode, which enhances the recruitment of CCR10+ T reg cells to the tumor site, thus inhibiting the functions of cytotoxic T cells and accelerating tumor growth." (PMID 38165484, 2024). "Furthermore, we did not examine whether other AP-1 members showed expression correlation with CCL28 and KRAS, or whether they regulated tumour growth." (PMID 37380804, 2023). "Under hypoxic conditions, HIF1A induces activation of target genes (PD-L1, CCL28, and GAL3ST1), resulting in immune cell apoptosis, and drives expression of the negative immune checkpoint regulator VSIR and MIC genes to evade immune surveillance and ultimately promote tumor immune escape." (PMID 35659268, 2022).
tumor (continued). "Moreover, hypoxia enhances the expression of CCL28 and TGF-β, which are involved in chemo-attracting Treg cells, regulating the inhibition efficacy of Teff cell responses, as well as contributing to angiogenesis and tumor tolerance." (PMID 33962639, 2021). "The considerable CXCL1-dependent inhibition of the expression of CCL2 and CCL28, also endowed with an immunostimulating, but also pro-tumoral effect, emphasizes the critical role of the final equilibrium among the multiple microenvironmental signals in driving BCSC fate and tumor behavior." (PMID 34195201, 2021). "However, numerous in vitro studies show that CCL28 and CCL27 support tumor development." (PMID 33076281, 2020). "Hypoxic tumor cells enhance Treg recruitment, through the production of CCL28 which interacts with CXCR10 (a proangiogenic and immunosuppressive molecule), the expression of neuropilin-1 (NP-1) which attracts Tregs in response to VEGF, or the secretion of the chemoattractant TGF-β by tumor cells." (PMID 30708988, 2019). "CCR10 and its ligand CCL28 are known to participate in the recruitment of tumor TReg lymphocytes, and a decrease in CD4+ CCR10+ cells may reflect a reduced global presence of CCR10-expressing TRegs and, therefore, a reduced recruitment of these cells by the tumor." (PMID 35740564, 2022). "In addition to its effect on cancer cells, CCL28 also acts on non-cancer cells in a tumor niche." (PMID 33076281, 2020). "The ratio of Treg cells was significantly decreased in tumour tissues of anti-CCL28-treated mice, but the ratios of CD8+ and CD4+ T cells were not changed by anti-CCL28 treatment in tumour tissues." (PMID 37380804, 2023). "This analysis led to the identification of the genes CX3CL1, CCL28, PROM1, and KLK5, which were highly expressed in the boundary cells and not in tumor cells, myoepithelial cells or any other colocalized cell type." (PMID 38114474, 2023).